LINC01104 (long independently transcribed non-coding RNA 1104)
Gene: Long non-coding RNA gene on chromosome 2 (100,208,152 to 100,254,182, forward strand). Ensembl gene ENSG00000232084.
Diseases named in the same sentence as LINC01104 in open-access papers:
LINC01104 is named in the same sentence as 3 diseases in open-access papers, as found by Europe PMC text mining. Sharing a sentence is not in itself a finding about the gene and the disease.
LINC01104 shares sentences with these, for which no sentence is quoted: Hypertension (1 paper); immune diseases (1); Obesity (1).